TTC16 (tetratricopeptide repeat domain 16)
Synonyms: FLJ32780
Tractability: PROTAC: ubiquitination databases record sites on it.
Gene: Protein-coding gene on chromosome 9 (127,716,079 to 127,731,590, forward strand). Ensembl gene ENSG00000167094.
Genetic constraint (gnomAD): Loss-of-function variants: 66 observed, 80.8 expected, observed/expected ratio (o/e) 0.82, 90% interval 0.67 to 1. The upper end of that interval is the gene's LOEUF score, 1, which puts it in group 4 of 6, group 1 being the genes least tolerant of losing a copy. Missense variants: 1,070 observed, 1,132.5 expected, observed/expected ratio (o/e) 0.94, 90% interval 0.9 to 0.99. Synonymous variants: 438 observed, 465.71 expected, observed/expected ratio (o/e) 0.94, 90% interval 0.87 to 1.02.
Homologues: Orthologues: chimpanzee TTC16 (99% identical), macaque TTC16 (92% identical), dog TTC16 (68% identical), pig TTC16 (65% identical), guinea pig TTC16 (54% identical), rat Ttc16 (51% identical), mouse Ttc16 (50% identical), tropical clawed frog ttc16 (25% identical), zebrafish ttc16 (22% identical). Paralogues in human: TTC7A (10% identical), CFAP70 (10% identical), TTC34 (10% identical), TTC7B (10% identical), TTC6 (9% identical), IFT88 (9% identical), TMTC3 (9% identical), BBS4 (8% identical), TMTC1 (8% identical), OGT (8% identical), TMTC2 (8% identical), TMTC4 (8% identical), and 2 more.
Diseases named in the same sentence as TTC16 in open-access papers:
TTC16 is named in the same sentence as 3 diseases in open-access papers, as found by Europe PMC text mining. Sharing a sentence is not in itself a finding about the gene and the disease.
TTC16 shares sentences with these, for which no sentence is quoted: immune disease (1 paper); melanoma (1); tumor (1).